IL1A (interleukin 1 alpha)
Diseases named in the same sentence as IL1A in open-access papers (continued):
Sharing a sentence is not in itself a finding about the gene and the disease.
dermatitis (19 papers, 2012 to 2025). An inflammatory process affecting the skin. "Compared with WT mice, KO mice showed an increased susceptibility to P. acnes-induced skin inflammation, as evidenced by higher levels of pro-inflammatory factors such as Cxcl1, Il-1α, Il-1β, Il-6 and Tnf-α in the knockout mice." (PMID 35414779, 2022). "They noted upregulation of IL-1α, IL-1RA, TNF-α and IL-1α /IL-1RA ratios, as well as time-dependent increase of IL-1B and observed some differences in the inflammatory mechanisms of incontinence-associated dermatitis, depending on the moisture source." (PMID 36555871, 2022). "The reduced subcutaneous level of this pro-inflammatory cytokine for IL1A −889 T allele would explain the protective effect of this allele against dermatitis." (PMID 25238536, 2014). "In a German study, the IL1A −889 T allele was also associated with a protective effect, with a lower prevalence of dermatitis in a group exposed to a high risk of skin irritability." (PMID 25238536, 2014). "Furthermore, to substantiate the pathogenic role of IL-1 in dermatitis and wasting syndrome, we treated normal healthy mice with recombinant IL-1α or IL-1β." (PMID 25119884, 2014). "Compared with wild-type mice, Rev-erbα-/- mice showed an increased sensitivity to P. acnes-induced skin inflammation, as evidenced by higher levels of pro-inflammatory factors such as Cxcl1, Il-1α, Il-1β, Il-6 and Tnf-α in the knockout mice." (PMID 35414779, 2022). "Compared with normal mice, jet-lagged mice were more sensitive to P. acnes-induced skin inflammation, as evidenced by higher levels of pro-inflammatory factors such as Cxcl1, Il-1α, Il-1β, Il-6 and Tnf-α." (PMID 35414779, 2022). "We crossed Il1a−/−, Il1b−/−, and Il1r1−/− mice onto the Flgft/ft background to investigate their contribution to spontaneous skin inflammation." (PMID 30937919, 2019). "Sharpincpdm and Sharpincpdm × Il1a−⁄− mice also showed a similar extent of dermatitis and splenomegaly at day 45 post birth." (PMID 27892465, 2016). "Altogether, these data suggest that IL-1α is dispensable for induction of dermatitis and cellular dysregulation in Sharpincpdm mice." (PMID 27892465, 2016). "The dog with peritonitis exhibited increased intracytoplasmic levels of IL-6, IL-12, IL-17A and TGF-β, whereas the dog with dermatitis presented increased expressions of IL-1α, IL-12 and TGF-β in lymphocytes." (PMID 26362860, 2015). "Skin scratching, cracking by xerosis and dermatitis promote the release of active IL-1α through a calcium-activated protease calpain and/or CTL/NK protease granzyme B mechanism." (PMID 25119884, 2014). "The IL-1ra/IL-1α ratio increases during infancy, irritant diaper dermatitis, heat rash, and erythema." (PMID 22988452, 2012). "IL-1 receptor antagonist (IL-1ra), IL-1α, and the ratio between these two molecules are useful for assessing skin reactivity and measuring skin inflammation." (PMID 22988452, 2012). "Since IL-1α plays a key role in the pathophysiology of many skin disorders, targeting IL-1α may provide an effective treatment to block the inflammatory process that drives a wide array of diseases, including dermatologic conditions such as AD." (PMID 39214920, 2024). "Initiation of skin inflammation by P. acnes involves activation of inflammatory cells, monocytes, keratinocytes and sebocytes and subsequent secretion of inflammatory cytokines and chemokines such as IL-1α, IL-1β, IL-6, IL-8 and TNF-α 43-45." (PMID 35414779, 2022). "Concerning the mode of action of icIL-1Ra1 in the skin, extracellular icIL-1Ra1 released by keratinocytes has been proposed to counter-regulate skin inflammation provoked by keratinocyte-derived IL-1α and/or by IL-1β, the latter mainly produced by infiltrating myeloid cells." (PMID 33796114, 2021).
dermatitis (continued). "Imiquimod-induced skin inflammation is partially reduced in mice deficient for both IL-1α/IL-1β or for IL-1R1, but not in IL-1α- or IL-1β-deficient mice, demonstrating the redundant activity of IL-1α and IL-1β for skin inflammation." (PMID 31156649, 2019). "To determine whether IL-1α promotes dermatitis in Sharpincpdm mice, we generated Sharpincpdm × Il1a−⁄− mice and observed these mice for signs of disease." (PMID 27892465, 2016). "While IL‐1α deficiency did not decrease the inflammatory score of Flgft/ft mice (P = 0.942), IL‐1β‐deficient Flgft/ft mice were protected from the development of skin inflammation (P = 0.013)." (PMID 30937919, 2019). "Although IL-1α did not provide any protection from dermatitis, we speculated that IL-1α deficiency would rescue the cellular dysregulation observed in Sharpincpdm mice." (PMID 27892465, 2016). "However, IL-1α deficiency did not provide any protection from dermatitis or systemic inflammation in Sharpincpdm mice." (PMID 27892465, 2016). "Further investigation on Sharpincpdm Il1a−/− mice and Sharpincpdm Il1b−/− revealed that IL-1β, but not IL-1α, delayed the onset of dermatitis at the median age of 60 days as compared to Sharpincpdm mice at the median age of 42.5 days." (PMID 40006996, 2025). "When the Sharpincpdm mice were crossed with mice deficient in the IL-1 receptor (Il1r−/−), which mediates signals from both IL-1α and IL-1β, the absence of IL-1R delayed the progression of dermatitis in the Sharpincpdm mice." (PMID 40006996, 2025). "Our results further show that the onset of dermatitis is specifically modulated by IL-1β, but not by IL-1α." (PMID 27892465, 2016). "Both IL-1α and IL-1β were dramatically increased in KIL-18Tg(+) mice after onset of dermatitis." (PMID 25119884, 2014). "Furthermore, we demonstrate a specific role for IL-1β, but not IL-1α, in instigating dermatitis in Sharpincpdm mice." (PMID 27892465, 2016). "However, whether IL-1α or IL-1β, both of which signals through IL-1R, instigates skin inflammation and systemic disease is not known." (PMID 27892465, 2016).
Peri-Implantitis (19 papers, 2014 to 2025). An inflammatory process with loss of supporting bone in the tissues surrounding functioning DENTAL IMPLANTS. "The subgroup of studies focusing on cytokine polymorphisms (IL-1A, IL-1B, IL-10, IL-17A) demonstrated variable associations with peri-implantitis risk." (PMID 41373620, 2025). "The results demonstrated that genotypes with the T allele in IL-1A-889C/T and IL-1B+3954C/T were significantly associated with an elevated risk of peri-implantitis and with more unfavorable clinical values." (PMID 41373620, 2025). "Although there is no consensus in the literature regarding the role of genetic polymorphisms in the development of peri-implantitis, most studies have focused on IL-1A -889, IL-1B +3954, and IL-1RN variable number of tandem repeats (VNTR) polymorphisms." (PMID 38203822, 2024). "Analysis of the association between IL-1A -889 polymorphism and the risk of peri-implantitis in dominant and recessive genetic models." (PMID 38203822, 2024). "Interleukin-1A (−889) is the main IL-1α variation that corresponds to an increased risk of peri-implantitis." (PMID 37232785, 2023). "It was found that there was a correlation between IL-1β +3953, together with IL-1α (−889), and an increased risk of peri-implantitis." (PMID 37232785, 2023). "Comparing both studies, for both IL-1A-889 and IL-1B+3954 polymorphisms, there is a higher percentage of T alleles in the peri-implantitis group and a higher percentage of C alleles in the health group." (PMID 35855430, 2022). "A recent meta-analysis found that carriers of positive genotype of IL-1A-889 and IL-1B+3954 had 1.95-fold risk of peri-implant disease (which included implant failure/loss, marginal bone loss and peri-implantitis)." (PMID 35855430, 2022). "Genotypic frequencies in polymorphisms of IL-1A-889 and IL-1B+3954, in the periimplant health group and in the peri-implantitis group." (PMID 35855430, 2022). "In the present study, we aimed to investigate the possible association of IL-1A- 889T and IL-1B+ 3954T polymorphisms with the peri-implantitis in a Portuguese cohort." (PMID 35855430, 2022). "For the IL-1A (−889) gene polymorphism, it was observed that the mutated allele was present in a higher percentage in the peri-implantitis group compared to the control group (30% vs 15% respectively, Fisher’s exact test, p = 0.45)." (PMID 35855430, 2022). "Allelic frequencies of polymorphisms of IL-1A-889 and IL-1B+3954 in the peri-implant health group and in the peri-implantitis group." (PMID 35855430, 2022). "We aimed to investigate if individuals carrying the genetic single nucleotide polymorphism (SNP) in the IL-1A (rs1800587) and IL-1B (rs1143634) genes are more susceptible to develop peri-implantitis." (PMID 35855430, 2022). "On the other hand, a recent meta-analysis concluded there was evidence of genetic effect (composite genotype IL-1A and IL-1B) on risk for implant failure and peri-implantitis." (PMID 26449434, 2015). "The conclusion drawn from this analysis indicates that IL-1A and IL-1B single-nucleotide polymorphisms (SNPs) could function as genetic markers of predisposition to peri-implantitis in the present population." (PMID 41373620, 2025). "We hypothesize that individuals carrying the T allele in the IL-1A-889 and IL-1B +3954 genes are more susceptible to develop peri-implantitis in comparison with individuals that don’t have these polymorphisms." (PMID 35855430, 2022). "In the future, it will be necessary to carry out more studies in this area, with larger samples, so that it is possible to identify and obtain results with greater accuracy and evidence regarding the relationship of polymorphisms of IL-1A-889 and IL-1B+3954 with the development of peri-implantitis." (PMID 35855430, 2022). "Thus, with the completion of the meta-analysis, it is observed that, in Caucasian European descendants, there is a significant association between the positive genotype IL-1A-889 and IL-1B +3954 with peri-implantitis." (PMID 35855430, 2022).
Peri-Implantitis (continued). "(2020) with a sample of 318 Chinese patients, the authors observed that subjects carrying the T allele of IL-1A -889 and IL-1B +3954 had a significant 2.27–2.47-fold and 1.9–1.99-fold increased risk of peri-implantitis, respectively, when using the CC genotype as reference." (PMID 35855430, 2022). "The development of easier diagnostic procedures and protocols may allow for better and cheaper diagnostics, especially for mixed IL-1α/IL-1β genotypes, thus allowing for the “tailor made” treatment of peri-implantitis and the early screening and maintenance of high-risk patients." (PMID 37232785, 2023). "However, individuals with the C/C genotype of the SNP IL-1β (− 511) and those with composite genotype IL1β (+ 3945) and IL-1α (− 889) may have a higher risk for peri-implantitis." (PMID 35061134, 2022). "Genotype frequencies of IL-1A -889, IL-1B +3954, and IL-1RN (VNTR) polymorphisms, in the peri-implant health group, in the peri-implantitis group, and in the total sample." (PMID 38203822, 2024). "The two most widely studied genetic variations, with respect to a possible relationship with peri-implantitis, are IL-1A-889T and IL-1B +3954T, which both have shown to be associated with changes in gene expression and protein secretion." (PMID 35855430, 2022). "In a total of 13 studies included, only four of these presented sufficient data regarding the relationship between genotype positive IL-1A-889 and IL-1B+3954 and peri-implantitis." (PMID 35855430, 2022). "After conducting this review, we found that only two authors demonstrated a significant association between the composite genotype of IL-1β (+ 3945) and IL-1α (− 889) and the presence of peri-implantitis." (PMID 35061134, 2022). "The close association of the four genetic variants IL-1a, IL-1b, TNF-a and IL-1RN with the risk of peri-implantitis development or implant loss has been demonstrated in a large number of worldwide association studies and was also confirmed in meta-analyses." (PMID 35819566, 2022). "At the oral level, several studies have demonstrated the presence of high levels of IL-1α and IL-1β in crevicular fluid and in saliva of patients with active peri-implantitis lesions." (PMID 30386510, 2018). "A recent cross-sectional study conducted in Portugal corrobated these findings concerning the investigated polymorphisms encoding for both IL-1α and ß in implant patients with and without peri-implantitis." (PMID 39182209, 2024). "Additionally, cytokines of IL-15, TNF-α, and IL-1α showed comparable amounts between healthy implants and peri-implantitis (p < 0.05)." (PMID 36233685, 2022). "Therefore, cooperating in the normal bone resorption of peri-implantitis, IL-1α is expressed in many types of cells in healthy tissues permanently, but its expression can be raised in response to proinflammatory, growth factors, and stress-associated stimuli." (PMID 33376734, 2020). "IL-1A-C889T, IL-1B+C3953T and IL-1RN+T2018C were identified by polymerase chain reaction (PCR) amplification in order to establish a relation between these variables and the presence of peri-implantitis." (PMID 26449434, 2015). "The aim was to evaluate the association between single-nucleotide polymorphisms (SNPs) in genes involved in inflammation and bone metabolism (BMP-4, BRINP3, CD14, FGF-3, FGF-10, GBP-1, IL-1α, IL-1β, IL-10, LTF, OPG, and RANKL) and peri-implantitis." (PMID 41373620, 2025). "In peri-implantitis, TNF-α, IL-1α, and IL-6 are significantly upregulated." (PMID 36768829, 2023).
atopic dermatitis (18 papers, 2014 to 2025). "In the phase 2b GENESIS study, bermekimab, an anti-IL-1α agent, was inferior to dupilumab in atopic dermatitis (AD), with only 16.7% of patients in both 350 mg and 700 mg bermekimab groups achieving EASI-75 at week 16, compared to 51.2% for dupilumab." (PMID 40004611, 2025). "Elevated levels of the precursor pro-inflammatory cytokine IL-1α were detected in atopic dermatitis skin models m2 and m3 after days 7 to 9 and days 9 to 12 compared to healthy controls." (PMID 36615633, 2023). "Previous studies investigating UV‐effects on skin and inflammatory skin diseases, such as atopic dermatitis, have reported a decrease in IL‐1α to IL‐1RA ratio as well as an increased IL‐1RA response at the exposed sites relative to control sites." (PMID 36872612, 2023). "Our previous results showed that histamine increases the secretion of the pro-inflammatory cytokines IL-1α, IL-6 and IL-8 in our atopic dermatitis skin models m2 and m3, when added at day 9 to the medium." (PMID 36615633, 2023). "Regarding other options for IL-1 blocking, a clinical study with bermekimab, an anti-IL-1α monoclonal antibody in patients with atopic dermatitis (NCT04990440) has been terminated due to low efficacy." (PMID 37199256, 2023). "It has also been reported that the ratio of IL-1α and the IL-1α receptor are significantly increased in patient samples with cutaneous inflammation such as atopic dermatitis and psoriasis." (PMID 28779153, 2017). "In previous reports, atopic dermatitis-like spongy changes and reduction of ceramide production induced by cytokines such as IL-1α and TNFα in epidermal cells were observed." (PMID 29132429, 2017). "IL-1a is a proinflammatory cytokine dysregulated in atopic dermatitis." (PMID 38558806, 2024). "Topical treatment regimen consisting of PPARα activator showed potent anti-inflammatory effects in murine models of atopic dermatitis and in irritant and allergic contact dermatitis, which were associated with reduction in pro-inflammatory cytokines TNF-α and IL-1α." (PMID 27611371, 2016). "Elevated levels of the pro-inflammatory cytokine IL-1α were detected in atopic dermatitis cytokine milieus with or without histamine after 1, 24 and 48 h compared to healthy control." (PMID 36615633, 2023).
lung fibrosis (18 papers, 2015 to 2025). "Furthermore, both IL-1α and IL-1β have been shown to be increased in mice following bleomycin challenge and IL-1α-, IL-1β- and IL-1R1-deficient mice are protected from bleomycin-induced pulmonary fibrosis." (PMID 27001429, 2016). "In addition, previous research has shown that Aptamin C more effectively suppresses the pro-inflammatory cytokines IL-1α and IL-6 than vitamin C, demonstrating that it may play a role in managing inflammation associated with pulmonary fibrosis." (PMID 39770419, 2024). "Emerging evidence has indicated that activation of the AIM2 inflammasome triggers TGF-β release in an IL-1α-dependent manner in peripheral blood mononuclear cells from patients with idiopathic pulmonary fibrosis." (PMID 39870644, 2025). "The pathophysiology of pulmonary fibrosis involves mitochondrial oxidation-driven overactivation of the AIM2 inflammasome via the production of IL-1α, IFN-α, and TGF-β." (PMID 36110858, 2022). "Together these data provide strong evidence that AIM2 inflammasome activation induces IL-1α release from circulating immune cells of PC patients with signs of lung fibrosis, implying systemic inflammation." (PMID 35844548, 2022). "In contrast, AIM2 stimulation in PBMCs from patients who presented lung fibrosis-like changes significantly increased (p=0.01) IL-1α levels (ctr: 34.75 ± 5.42 pg/ml vs PolydA:dT: 81.6 ± 16.5 pg/ml)." (PMID 35844548, 2022). "In particular, 19 out of 23 (82.6%) severe PC and 8 out of 29 (27.6%) moderate PC patients presented signs of lung fibrosis, associated to lower levels of IFN-β, but higher IL-1α and TGF-β." (PMID 34944747, 2021). "It was recently suggested that higher plasma levels of IL-1α and TGF-β and lower levels of IFN-β could point to a greater risk of changes similar to those observed in pulmonary fibrosis in patients after COVID-1917." (PMID 38360855, 2024). "Notably, IL-1α release was observed in 18 out of 24 PC patients with lung fibrosis-like changes (75%) after AIM2 activation." (PMID 35844548, 2022). "Furthermore, our group has previously shown that prophylactic administration of BMMCs reduced mRNA levels of TGF-β, IL-1β, IL-1α, and IL-1RN and attenuated silica-induced lung fibrosis." (PMID 29126438, 2017). "Given the clear importance of IL-1α, IL-1β and IL-33 in lung fibrosis and the likely compensatory action provided by members of the IL-1 cytokine family in vivo, targeting the shared receptors (for example, IL-1RAcP) may be more effective." (PMID 27001429, 2016). "Therefore, the inverse relationship between IFN-β vs IL-1α and TGF-β could be at the crossroad, defining PC patients susceptible to lung fibrosis." (PMID 34944747, 2021). "In contrast, PBMCs from PC patients who exhibited lung fibrosis markers displayed heightened AIM2 activation, leading to the release of IL-1α, IFN-α, and TGF-β." (PMID 40072090, 2025). "In this context, we found that both CD14+ and CD14+HLA-DR+ PBMCs from PC patients with signs of lung fibrosis expressed higher levels of AIM2 and confirmed the release of IL-1α and TGF-β after its triggering." (PMID 35844548, 2022). "In sharp contrast, PBMCs from PC patients with signs of lung fibrosis were highly responsive to AIM2 activation, which induced the release of IL-1α, IFN-α and TGF-β." (PMID 35844548, 2022). "In our previous studies, we showed that absent in melanoma 2 (AIM2) inflammasome, a multimeric protein complex, was responsible for the release of IL-1α and TGF-β by peripheral blood mononuclear cells (PBMCs) of idiopathic pulmonary fibrosis (IPF) patients." (PMID 35844548, 2022). "On the other hand, severe or moderate PC patients who developed lung fibrosis-like changes had lower levels of IFN-β, but higher levels of IL-1α and TGF-β." (PMID 34944747, 2021). "In our previous study, we observed that IL-1α and TGF-β were highly released by peripheral blood mononuclear cells (PBMCs) obtained by patients with idiopathic pulmonary fibrosis (IPF)." (PMID 34944747, 2021).